PTX3 (pentraxin 3)
Diseases named in the same sentence as PTX3 in open-access papers (continued):
Sharing a sentence is not in itself a finding about the gene and the disease.
pneumonia (15 papers, 2010 to 2025). An acute, acute and chronic, or chronic inflammation focally or diffusely affecting the lung parenchyma, caused by an infection in one or both of the lungs (by bacteria, viruses, fungi, or mycoplasma.). "The diagnostic accuracy of PTX3 as local marker of infection has been strengthened by the observation that its levels can identify microbiologically confirmed pneumonia in BALF and plasma of mechanically ventilated patients." (PMID 31031772, 2019). "The diagnostic accuracy of PTX3 was confirmed when we limited our analyses only to proven bacterial pneumonia cases or to patients who fulfilled clinical criteria for pneumonia at the time of BAL fluid sampling." (PMID 25314919, 2014). "In a convenience sample of intubated critically ill patients undergoing BAL as per clinical decision, alveolar PTX3 was an early marker of microbiologically confirmed pneumonia with better diagnostic accuracy than other biomarkers." (PMID 25314919, 2014). "In recent years, Pancreatic Stone Protein (PSP) and Pentraxin 3 (PT3) have emerged as biomarkers of interest in pneumonia." (PMID 41302121, 2025). "Gene expression analysis revealed significant upregulation of immune-related markers (TLR2, CLEC4E, PTX3, CXCL8, IL15RA) and notable SNP variations associated with pneumonia susceptibility." (PMID 40559821, 2025). "Using PCR-DNA sequence verdicts, the TLR2 (354 bp), CLEC4E (443 bp), PTX3 (363 bp), CXCL8 (300 bp), SOCS3 (480 bp) and IL15RA (378 bp) genes were found to have different SNPs in the amplified DNA bases linked to pneumonia." (PMID 40559821, 2025). "It has been demonstrated that PTX3 can identify various infectious organisms, including bacteria, viruses, and fungi, and can improve their removal during experimental pneumonia." (PMID 39294659, 2024). "Several studies investigated the serum, pleural effusion, and alveolar levels of PTX3 in patients with pneumonia." (PMID 29861799, 2018). "Animal studies have shown that, during pneumonia, PTX3 participates in fine-tuning of inflammation (for example, microbial clearance and recruitment of neutrophils)." (PMID 25314919, 2014). "PTX3 levels in BAL fluid predicted pneumonia with an area under the receiving operator curve of 0.815 (95% CI =0.710 to 0.921, P <0.0001), whereas none of the other biomarkers were effective." (PMID 25314919, 2014). "In univariate prediction analysis, PTX3 levels ≥1 ng/ml in BAL fluid significantly predicted pneumonia (β =2.784, SE =0.792, P <0.001); all other biomarkers were not effective." (PMID 25314919, 2014). "In our study, alveolar PTX3 was an independent marker of pneumonia due to any etiology with elevated NRI values in comparison to other mediators and to CPIS." (PMID 25314919, 2014). "In particular, PTX3 levels ≥1 ng/ml in BAL fluid predicted pneumonia in univariate analysis (β =2.784, SE =0.792, P <0.001) with elevated sensitivity (92%), specificity (60%) and negative predictive value (95%)." (PMID 25314919, 2014). "AUCROC analysis showed that PTX3 levels in BAL fluid predicted pneumonia (AUCROC =0.815, 95% CI =0.710 to 0.921, P <0.0001), whereas BAL fluid levels of sTREM-1, plasma PTX3, sTREM-1, CRP and PCT did not." (PMID 25314919, 2014). "During experimental pneumonia, PTX3 has been shown to recognize different infectious agents (that is, bacteria, viruses and fungi) and to enhance their clearance, primarily by regulation of neutrophil recruitment." (PMID 25314919, 2014). "This indicates that PTX3 levels ≥1 ng/ml in BAL fluid only rarely misclassify a patient with pneumonia as being uninfected." (PMID 25314919, 2014). "The aim of the present study was to determine a threshold level of alveolar PTX3 with elevated sensitivity and specificity for microbiologically confirmed pneumonia." (PMID 25314919, 2014). "Net reclassification index PTX3 values ≥1 ng/ml in BAL fluid for pneumonia indicated gain in sensitivity and/or specificity vs. all other mediators." (PMID 25314919, 2014).
pneumonia (continued). "When triggered, a systemic inflammatory response carried on by severe pneumonia may lead the body to release more PTX3 into the blood." (PMID 39294659, 2024). "Our data thus lead us to the working hypothesis that PTX3 level in BAL fluid is discriminative of confirmed pneumonia in intubated ICU patients." (PMID 25314919, 2014). "Of the two patients with pneumonia and PTX3 level <1 ng/ml in BAL fluid, one had bacterial CAP and the other had fungal HAP and immunosuppression (which could have determined low PTX3 levels)." (PMID 25314919, 2014). "A cutoff level of PTX3 ≥ 1 ng/ml in BAL fluid (identified by Youden index) was associated with 92% sensitivity, 60% specificity, 49% PPV and 95% NPV for culture-positive pneumonia." (PMID 25314919, 2014). "In univariate prediction analysis, PTX3 levels ≥7 ng/ml in BAL fluid significantly predicted pneumonia (β =2.931, SE =0.768, P <0.001), whereas all other mediators could not predict bacterial pneumonia." (PMID 25314919, 2014). "We determined the PTX3 threshold in BAL fluid for pneumonia and compared it to other biomarkers." (PMID 25314919, 2014). "In the future, adequately powered prospective trials may validate PTX3 level measured in BAL fluid assays as a marker of pneumonia and test whether it has any clinical value in guiding prescription of antibiotics." (PMID 25314919, 2014). "In this hypothesis-generating convenience sample, a PTX3 level ≥1 ng/ml in BAL fluid was discriminative of microbiologically confirmed pneumonia in mechanically ventilated patients." (PMID 25314919, 2014). "Importantly, in a Klebsiella-induced pneumonia model, PTX3 is protective when a low inoculum is given to the mice but detrimental when a high inoculum is given." (PMID 20920344, 2010). "The genes TLR2, CLEC4E, PTX3, CXCL8, and IL15RA exhibited significantly higher expression levels in pneumonia-affected ewes compared to healthy controls." (PMID 40559821, 2025). "This study used a PCR-DNA sequencing technique to characterize the immunological (TLR2, CLEC4E, PTX3, CXCL8, SOCS3 and IL15RA) genes in ewes with pneumonia and healthy ewes." (PMID 40559821, 2025). "Thus, our study indicates that, in intubated critically ill patients, the accuracy of PTX3 levels in BAL fluid for diagnosing pneumonia might be superior to other current biomarkers and clinical markers, especially when nonbacterial and/or non-VAP cases are suspected." (PMID 25314919, 2014). "The aim of the present study was to describe the use of PTX3 levels in BAL fluid as a potentially new marker for early and accurate diagnosis of pneumonia." (PMID 25314919, 2014). "In any case, it is not surprising that alveolar, but not serum, PTX3 has been disclosed as a valuable early marker for microbiologically-confirmed pneumonia." (PMID 29238334, 2017). "PTX3 levels in BAL fluid was the only mediator significantly higher in the presence of pneumonia compared to noninfection cases (P <0.0001)." (PMID 25314919, 2014). "PTX3 was shown to predict bloodstream infection and severe disease in febrile patients admitted to emergency departments, indicated acute respiratory distress syndrome (ARDS) in critically ill patients, and correlated with pneumonia severity and length of hospital stay in adults with CAP." (PMID 31031772, 2019). "We also hypothesize that higher PTX3 levels could influence disease course and be associated with the necessity of hospitalization due to SARS-CoV-2 virus infection, even though we did not observe any differences in this hepatokine concentration between patients with and without pneumonia." (PMID 34680053, 2021). "In patients with community-acquired pneumonia (CAP), the plasma concentration of PTX3, but not CRP, was correlated with the severity of CAP based on the pneumonia severity index (PSI), CURB-65, Acute Physiology and Chronic Health Evaluation (APACHE) II scores, and the length of hospital stay." (PMID 25530683, 2014).
liver fibrosis (14 papers, 2008 to 2025). "Plasma PTX-3 levels in our study were significantly higher in subgroups with a high risk of advanced liver fibrosis assessed based on the FIB-4 scores and NFSs." (PMID 40066165, 2025). "The assessment of liver fibrosis based on the HFS showed the highest PTX-3 levels in men with undermined risk and women with a significant risk of advanced fibrosis." (PMID 40066165, 2025). "Anyhow, a separate study described an association of plasma PTX3 with the stages of liver fibrosis in patients with NAFLD." (PMID 32078718, 2020). "The study found that PTX3 provided clinically relevant diagnostic accuracy as a single marker of liver fibrosis." (PMID 31061822, 2019). "Only one study concerning the PTX3 polymorphism analyzed the ability of serum PTX3 levels to predict liver fibrosis in HCV patients." (PMID 31061822, 2019). "Close associations between PTX3 levels, disease progression, and the stages of liver fibrosis in patients with nonalcoholic fatty liver disease and alcoholic hepatitis were shown." (PMID 31061822, 2019). "A more detailed study revealed that plasma PTX3 levels can be used to differentiate between stages 3–4 NAFLD and stages 0–2 NAFLD, and that higher plasma PTX3 levels in NAFLD patients are associated with severe stages of hepatic fibrosis." (PMID 19014569, 2008). "However, when the risk of liver fibrosis was calculated according to NFSs, plasma PTX-3 levels were significantly higher in both men and women with advanced fibrosis." (PMID 40066165, 2025). "Furthermore, lower PTX3 levels were associated with liver fibrosis progression whereas in mouse models PTX3 deficiency was associated with excessive fibrin accumulation, augmented collagen deposition and defective tissue repair." (PMID 34777248, 2021). "The empirical cutoff points for PTX-3 levels as a potential marker of liver fibrosis were assessed separately for women and men." (PMID 40066165, 2025). "In our study, plasma PTX-3 levels were significantly higher in both women and men with liver fibrosis assessed based on FIB-4." (PMID 40066165, 2025). "We have tried to establish the empirical cutoff point for PTX-3 level as a marker of liver fibrosis assessed based on FIB-4, NFS, and HFS system values, separately for men and women." (PMID 40066165, 2025). "The cutoff points for PTX-3 levels based on all significant ROC curve analyses, as a marker of liver fibrosis, ranged from 1.96 to 2.30 ng/mL (an AUC ranging between 0.596 and 0.643, sensitivity from 39.1 to 61.7%, and specificity from 56.1 to 79.6%) in women." (PMID 40066165, 2025). "Clinically, serum PTX3 has shown promise as a non-invasive biomarker for assessing liver fibrosis in patients with chronic hepatitis C virus (HCV) infection." (PMID 41462970, 2025). "In our study, we observed a significant increase in PTX3 immunoreactivity in liver tissue in advanced stages of liver fibrosis of CHB." (PMID 41462970, 2025). "Based on the multivariable analysis of non-invasive biomarkers, including PTX3, the model predicting liver fibrosis, the Pentra score was proposed." (PMID 39519095, 2024). "PTX-3 expression contributes to increased synthesis of extracellular protein matrix, suggesting a possible role in liver fibrosis." (PMID 37291355, 2023). "PTX-3 demonstrates a significant positive correlation with the disease activity index and the severity of fatty degeneration and liver fibrosis in adults with NAFLD." (PMID 35059041, 2021). "There was also a significant correlation between PTX3 levels and indirect serum markers of liver fibrosis, including APRI index, FIB-4 score, and GPR ratio (P < 0.001 each)." (PMID 31061822, 2019). "Our study clearly demonstrated that the PTX3 level in HCV patients increased with the progression of liver fibrosis stage." (PMID 31061822, 2019).
liver fibrosis (continued). "The AUCs of reported fibrosis markers (APRI index, FIB‐4 score, GPR ratio, HA, TGF-β1, and LSM values) increased as the liver fibrosis stages progressed; the AUC of PTX3 increased accordingly as well." (PMID 31061822, 2019). "In the new study (a manuscript for an article is in preparation), based on our finding showing a significant correlation of the PTX3 value with the degree of liver fibrosis, we combined the PTX3 and HA or TGF-β1 values and defined a new index." (PMID 31061822, 2019). "In light of these observations, further clinical studies are needed to elucidate the precise role of the PTX3 in liver fibrosis." (PMID 31061822, 2019). "PTX3 significantly correlated with the histological stage of liver fibrosis (rho = 0.64, P < 0.001), and the levels of PTX3 were significantly higher in patients with significant fibrosis (F≥2) compared to F0-F1 (P < 0.001)." (PMID 31061822, 2019). "The PTX3 values were closely correlated with the stages of liver fibrosis (p < 0.0001, Kruskal-Wallis test)." (PMID 19014569, 2008). "Additionally, PTX3 levels have been shown to correlate with the severity of liver fibrosis in both NASH and HCV infection." (PMID 41462970, 2025). "Thus, further studies are required to elucidate the role of PTX-3 as a marker of liver fibrosis in older adults." (PMID 40066165, 2025). "Another factor reducing the cutoff point value and sensitivity and specificity of PTX-3 as a marker of liver fibrosis may be the fatty liver and NASH duration." (PMID 40066165, 2025). "In this context, it is worth searching for plasma PTX-3 concentrations as a potential biomarker that could replace non-invasive liver fibrosis tests." (PMID 40066165, 2025). "Accordingly, plasma PTX3 was high in HCC compared to patients with severe liver fibrosis." (PMID 32078718, 2020). "PTX3 levels were also related to the severity of liver fibrosis in NASH30 and HCV infection." (PMID 33219288, 2020). "Since the classic short pentraxin CRP is produced in the liver, it is thought that CRP levels in NAFLD may be a more sensitive marker for predicting severity of liver fibrosis when compared to PTX3 levels." (PMID 26997950, 2016). "The aim of the present study was to investigate whether PTX3 can be a new noninvasive marker for prediction of liver fibrosis in patients with NAFLD." (PMID 26997950, 2016). "However, we have not found any descriptions of the importance of PTX 3 in determining the phenotype of Crohn’s disease, although its connection to tissue remodeling, as well as the usefulness of PTX3 measurements in monitoring the advancement of liver fibrosis, has been demonstrated." (PMID 39519095, 2024). "The experiments in cell showed that while PTX3 is mainly expressed in neutrophils in healthy liver; in injury it is mainly expressed in hepatic stellate cells (HSCs), the main cell type responsible for the reparative response after tissue injury and liver fibrosis." (PMID 31061822, 2019). "PTX3 could be an alternative noninvasive serum marker for liver biopsy to assess liver fibrosis." (PMID 31061822, 2019). "Our study suggests that plasma PTX-3 levels are not sensitive enough to be used as a non-specific marker of liver fibrosis in older adults." (PMID 40066165, 2025). "There are no studies exploring the relationship between plasma PTX-3 levels and liver fibrosis in older adults." (PMID 40066165, 2025). "Our results correspond with those obtained in middle-aged subjects, where plasma PTX-3 levels were significantly higher in stage F3–F4 than F0–F2 NAFLD cases, and plasma PTX-3 concentrations correlated with stages of liver fibrosis regardless of sex." (PMID 40066165, 2025). "In HCV-related HCC patients, PTX3 was high compared to non-cancer patients with mild or severe liver fibrosis." (PMID 32078718, 2020). "Thus, we showed that the baseline plasma PTX3 level is not only a strong clinical marker of NASH, but also of the severity of liver fibrosis in NAFLD patients." (PMID 19014569, 2008).
liver fibrosis (continued). "We hypothesized that plasma PTX3 levels increase in patients with NASH, and investigated the clinical usefulness for the diagnosis and staging of liver fibrosis in NASH patients." (PMID 19014569, 2008). "Moreover, the usefulness of PTX-3 as a biomarker of liver fibrosis in the older population has not been assessed so far." (PMID 40066165, 2025). "Plasma PTX3 measurements may be noninvasive and appear to show promise as a means to differentiate NASH from non-NASH patients, and as a clinical marker of the severity of liver fibrosis in NASH patients." (PMID 19014569, 2008). "The results suggest that plasma PTX3 levels may not only be laboratory values that differentiate NASH from non-NASH, but marker of the severity of hepatic fibrosis in NASH." (PMID 19014569, 2008).
type 2 diabetes (14 papers, 2013 to 2025). "Recently, elevated serum PTX3 levels have been linked to type 2 diabetes in obese patients with nonalcoholic fatty liver disease." (PMID 39657836, 2025). "In this study, PTX3, an essential component of innate immunity, and a novel cardiovascular risk factor, also in patients with type 2 diabetes was the strongest predictor of PCSK9 levels in multiple stepwise regression analysis." (PMID 35024053, 2021). "Studies have suggested that PTX-3 is strongly associated with the occurrence of such diseases as type II diabetes, atherosclerosis, and septicemia." (PMID 35059041, 2021). "Interestingly, we found that the levels of suPAR, sICAM-1, sTie-2, Ang-2, PTX3 and PCT were associated with coma and that sEPCR, sICAM-1, suPAR, sTie-2, Ang-2 and PTX3 were associated with fatality." (PMID 35204613, 2022). "Besides, suPAR, sTie-2, Ang-2, sICAM-1, PCT and PTX3 were associated with coma, and PTX3 was the more promising biomarker of coma with an odd of 1.09 and an AUC of 0.78." (PMID 35204613, 2022). "In this context it is worth noting that the human PTX3 gene is located in a chromosomal region (chromosome 3, band q25) that is identified as a major locus for susceptibility to diabetic nephropathy in both type 1 and type 2 diabetes." (PMID 23658833, 2013). "In a study conducted on 270 patients with type 2 diabetes in Japan, it was reported that three months of sitagliptin treatment resulted in a decrease in PTX-3 levels compared to baseline values (1.88 (0.78)-1.65 (0.63) ng/ml; p=0.0038)." (PMID 38510866, 2024). "The present study aimed to evaluate the effect of DPP-4 inhibitors on sMMSE scores, serum BDNF, and PTX-3 levels in patients with type 2 diabetes, compared with patients who only use metformin treatment." (PMID 38510866, 2024). "Accordingly, serum PTX3 was positively correlated with LDL-cholesterol in a cohort of type 2 diabetes patients." (PMID 32078718, 2020). "This study aimed to evaluate the association between DPP-4 inhibitor use and cognitive functions, serum brain-derived neurotrophic factor (BDNF), and pentraxin-3 (PTX-3) levels in patients with type 2 diabetes, compared with the patients who only use metformin treatment." (PMID 38510866, 2024). "Conversely, marked decreases in PTX3 levels were associated with decreased albuminuria and improved flow-mediated dilatation following a 12 week intervention with ACE-inhibitors (ramipril) in type 2 diabetic patients." (PMID 23658833, 2013). "A recent study showed that serum PTX-3 expression level is significantly higher in patients with a type II diabetes comorbidity and NAFLD than that in diabetic patients, and PTX-3 is positively correlated with TC, LDL-C, and TGs." (PMID 35059041, 2021). "In the current study, we investigated the plasma PTX3 levels in 296 Malay subjects including the subjects with normal glucose tolerance (NGT) and type 2 diabetes (T2DM) patients with or without DN by using an enzyme-linked immune-sorbent assay." (PMID 24350299, 2013).